AR (androgen receptor)
Description:
Steroid hormone receptors are ligand-activated transcription factors that regulate eukaryotic gene expression and affect cellular proliferation and differentiation in target tissues. Transcription factor activity is modulated by bound coactivator and corepressor proteins like ZBTB7A that recruits NCOR1 and NCOR2 to the androgen response elements/ARE on target genes, negatively regulating androgen receptor signaling and androgen-induced cell proliferation. Transcription activation is also down-regulated by NR0B2. Activated, but not phosphorylated, by HIPK3 and ZIPK/DAPK3. [Isoform 3]: Lacks the C-terminal ligand-binding domain and therefore constitutively regulates the transcription of a specific set of canonical AR-target genes, including PSA/KLK3 and TMPRSS2, independently of steroid hormones. However, some genes are differentially regulated by full-length AR (isoform 1) and isoform 3. Isoform 3-specific target genes may be regulated independently of FOXA1 expression. [Isoform 4]: Lacks the C-terminal ligand-binding domain and may therefore constitutively activate the transcription of a specific set of genes independently of steroid hormones.
Synonyms: DHTR; NR3C4; AIS; SMAX1; HUMARA; AR8; HPCX3; HYSP1; KD; SBMA; TFM
Tractability: Small molecule: an approved drug acts on it; a structure with a bound ligand is known; a high-quality ligand is known; it has a high-quality binding pocket; it belongs to a druggable protein family. Antibody: its Gene Ontology location is reachable by antibodies, with medium confidence. PROTAC: a drug acting on it is in phase 2 or 3 trials; it is named in the literature on targeted protein degradation; UniProt records ubiquitination sites on it; ubiquitination databases record sites on it; a small molecule that binds it is known.
Target class: Nuclear hormone receptor subfamily 3 group C member 4; Transcription factor; Nuclear hormone receptor subfamily 3 group C; Nuclear hormone receptor subfamily 3; Nuclear receptor
Chemical probes: ARCC-4 (high quality), ARD-266 (high quality), BICALUTAMIDE, CHEMBL2323490, CHEMBL2323507, HYDROXYFLUTAMIDE, INDOMETHACIN, LGD-2226, PD088617, PROTAC-AR-Degrader-4
Safety:
Unwanted effects reported when the protein is acted on. In parentheses: how it was acted on, where the effect was seen, and who reports it.
Decrease, Population growth rate (activation; source: AOP-Wiki)
androgenicity females (activation; endocrine; source: Bowes et al. (2012))
anemia (inhibition, acute dosing; central nervous system, endocrine; source: Lynch et al. (2017))
bone metastasis (inhibition, acute dosing; central nervous system, endocrine; source: Lynch et al. (2017))
bone pain (inhibition, acute dosing; central nervous system, endocrine; source: Lynch et al. (2017))
death (inhibition, acute dosing; central nervous system, endocrine; source: Lynch et al. (2017))
decreased anxiety (activation, acute dosing; central nervous system, endocrine; source: Lynch et al. (2017))
decreased attention (inhibition, acute dosing; central nervous system, endocrine; source: Lynch et al. (2017))
decreased memory (inhibition, acute dosing; central nervous system, endocrine; source: Lynch et al. (2017))
decreased spermatogenesis (inhibition; endocrine; source: Bowes et al. (2012))
depression (inhibition, acute dosing; central nervous system, endocrine; source: Lynch et al. (2017))
drug abuse/dependence (activation, acute dosing; central nervous system, endocrine; source: Lynch et al. (2017))
gynecomastia (inhibition; endocrine; source: Bowes et al. (2012))
heart attack (inhibition, acute dosing; central nervous system, endocrine; source: Lynch et al. (2017))
hot flashes (inhibition, acute dosing; central nervous system, endocrine; source: Lynch et al. (2017))
Impaired recruitment , Population trajectory (inhibition; source: AOP-Wiki)
impotence (inhibition; endocrine; source: Bowes et al. (2012))
Increase, hepatocellular adenomas and carcinomas (activation; source: AOP-Wiki)
Increase, Leydig cell tumors (inhibition; source: AOP-Wiki)
increased body weight (inhibition, acute dosing; central nervous system, endocrine; source: Lynch et al. (2017))
increased breast carcinoma (inhibition; endocrine; source: Bowes et al. (2012))
increased hostility (activation; endocrine; source: Bowes et al. (2012))
increased muscle mass (activation; endocrine; source: Bowes et al. (2012))
increased prostate carcinoma (activation; endocrine; source: Bowes et al. (2012))
increased triglycerides (inhibition, acute dosing; central nervous system, endocrine; source: Lynch et al. (2017))
insulin resistance (inhibition, acute dosing; central nervous system, endocrine; source: Lynch et al. (2017))
liver complications (activation; endocrine; source: Bowes et al. (2012))
mastodynia (inhibition; endocrine; source: Bowes et al. (2012))
N/A, Impairment of reproductive capacity (inhibition; source: AOP-Wiki)
oedema (activation; endocrine; source: Bowes et al. (2012))
and 3 more effects
Gene: Protein-coding gene on chromosome X (67,543,353 to 67,730,619, forward strand). Ensembl gene ENSG00000169083.
Subcellular location: Nucleus; Cytoplasm
Subcellular location (Human Protein Atlas): Cytosol
Pathways (Reactome):
Gene expression (Transcription): Nuclear Receptor transcription pathway; RUNX2 regulates osteoblast differentiation
Metabolism of proteins: SUMOylation of intracellular receptors; Ub-specific processing proteases
Cellular responses to stimuli: HSP90 chaperone cycle for steroid hormone receptors (SHR) in the presence of ligand
Signal Transduction: Activated PKN1 stimulates transcription of AR (androgen receptor) regulated genes KLK2 and KLK3
Gene Ontology:
Molecular function: androgen binding; ATPase binding; beta-catenin binding; chromatin binding; DNA-binding transcription activator activity, RNA polymerase II-specific; DNA-binding transcription factor activity; enzyme binding; molecular adaptor activity; molecular condensate scaffold activity; nuclear receptor activity; nuclear steroid receptor activity; protein binding; RNA polymerase II cis-regulatory region sequence-specific DNA binding; RNA polymerase II general transcription initiation factor binding; RNA polymerase II transcription regulatory region sequence-specific DNA binding; RNA polymerase II-specific DNA-binding transcription factor binding; signaling receptor binding; transcription cis-regulatory region binding; transcription coactivator binding; DNA-binding transcription factor activity, RNA polymerase II-specific; estrogen response element binding; DNA binding; POU domain binding; RNA polymerase II core promoter sequence-specific DNA binding; sequence-specific DNA binding; and 3 more
Biological process: androgen receptor signaling pathway; cellular response to estrogen stimulus; cellular response to steroid hormone stimulus; cellular response to testosterone stimulus; estrogen receptor signaling pathway; intracellular receptor signaling pathway; membraneless organelle assembly; negative regulation of cell population proliferation; negative regulation of extrinsic apoptotic signaling pathway; negative regulation of transcription by RNA polymerase II; positive regulation of cell differentiation; positive regulation of cell population proliferation; positive regulation of DNA-templated transcription; positive regulation of gene expression; positive regulation of integrin biosynthetic process; positive regulation of miRNA transcription; positive regulation of transcription by RNA polymerase II; positive regulation of transcription by RNA polymerase III; regulation of protein localization to plasma membrane; cell-cell signaling; male gonad development; response to testosterone; signal transduction; spermatogenesis; regulation of DNA-templated transcription
Cellular component: chromatin; cytoplasm; cytosol; nuclear speck; nucleus; protein-containing complex; transcription repressor complex; nucleoplasm; plasma membrane
Gene-disease validity (ClinGen):
ClinGen rates the evidence that AR causes each of these diseases.
Kennedy disease (X-linked): Definitive. Kennedy's disease, also known as bulbospinal muscular atrophy (BSMA), is a rare X-linked recessive motor neuron disease characterized by proximal and bulbar muscle wasting.
Cancer hallmarks: escaping programmed cell death (promotes); proliferative signalling (promotes)
Homologues: Orthologues: chimpanzee AR (99% identical), macaque AR (96% identical), pig AR (90% identical), rabbit AR (90% identical), rat Ar (87% identical), mouse Ar (86% identical), guinea pig AR (85% identical), tropical clawed frog ar (55% identical), zebrafish ar (38% identical), Drosophila melanogaster ERR (11% identical). Paralogues in human: NR3C2 (29% identical), PGR (27% identical), NR3C1 (24% identical), ESR2 (13% identical), ESR1 (13% identical), ESRRB (12% identical), ESRRG (12% identical), ESRRA (11% identical).
Diseases named in the same sentence as AR in open-access papers:
AR is named in the same sentence as 784 diseases in open-access papers, as found by Europe PMC text mining. Sharing a sentence is not in itself a finding about the gene and the disease. The quoted sentences say what the papers report.
prostate carcinoma (5,783 papers, 1999 to 2026). A carcinoma that arises from epithelial cells of the prostate gland. "LEF1 regulates the expression of the androgen receptor and is associated with the invasive ability of prostate cancer." (PMID 41516419, 2026). "We have shown that UHRF1 is highly expressed in enzalutamide-resistant prostate cancer cells and its expression correlates with the loss of AR-dependent glandular features." (PMID 41760602, 2026). "Lineage plasticity has emerged as an important mechanism of treatment resistance in prostate cancer, increasingly associated with loss of androgen receptor (AR) signaling, and in many cases induction of stemness phenotypes and neuroendocrine features." (PMID 41760602, 2026). "Human epidermal growth factor receptor 2 (HER2) is a molecular target of interest in prostate cancer due to its association with poor prognosis and its potential role in androgen receptor signaling." (PMID 41744855, 2026). "Where AR upregulation is found in prostate cancer, the ATM (ataxia telangiectasia mutated) gene’s downregulation, or complete loss, is found." (PMID 40699691, 2025). "TET2, which is a critical gene involved in androgen receptor (AR) signaling exhibits reduced expression in prostate cancer and is associated with adverse clinical outcomes, including elevated Gleason scores and increased metastatic potential." (PMID 40297177, 2025). "Loss of AR signaling and AR independence in prostate cancer is one of the major drivers of CRPC and its more lethal and aggressive subtype, treatment-induced neuroendocrine prostate cancer (t-NEPC)." (PMID 40115748, 2025). "The important question is, if it is known that androgen receptor blockades in their many forms eventually cause castration-resistant prostate cancer, why is it used as a frontline therapy?" (PMID 40427006, 2025). "Prostate cancer, one of the most common male malignancies, is closely associated with abnormal AR signaling pathway activation." (PMID 41049269, 2025). "In endocrine therapy for breast and prostate cancers, resistance-associated mutations in ER and AR have been documented." (PMID 40499006, 2025). "Restoration of downstream mTOR signaling causes resistance to combined Akt and androgen receptor blockade in prostate cancer." (PMID 39919177, 2025). "NSE is a biomarker of neuroendocrine differentiation in prostate cancer and has been associated with poor prognosis and resistance to androgen receptor (AR)-targeted therapy." (PMID 41209857, 2025). "In the case of androgen signaling, ADP ribosylation and turnover of chromatin-associated AR illustrate how PARP-mediated degradation of a transcription factor can shape the transcriptome of prostate cancer cells." (PMID 40681873, 2025). "Systems approaches can similarly be used in prostate cancer to model and predict how AR mutations, AR amplifications, AR variants, or alternative signaling pathways facilitate therapy resistance." (PMID 40840524, 2025). "Our findings highlight key genetic regions and genes that affect cancer-related pathways and androgen receptor (AR) signaling, providing new insight into how inherited variants shape prostate cancer susceptibility." (PMID 41468516, 2025). "These articles were chosen based on their direct relevance to SPOP mutations in prostate cancer, their contributions to disease characterization, and their insights into therapeutic implications related to the AR signaling pathway." (PMID 40432836, 2025).
prostate carcinoma (continued). "Androgen deprivation therapy (ADT) is widely utilized because of its association with abnormal androgen and androgen receptor (AR) signaling in the majority of prostate cancers." (PMID 40705122, 2025). "Prostate-specific antigen (PSA) is a diagnostic biomarker for prostate cancer, whose regulation is mediated by the binding of testosterone to androgen receptor (AR)." (PMID 41367482, 2025). "Researchers have applied RT-ddPCR to measure clinically relevant exRNAs like androgen receptor splice variant 7 (AR-V7) mRNA in exosomes of prostate cancer patients, detecting this therapy-resistance marker in plasma with high sensitivity." (PMID 41008718, 2025). "This review explains how the androgen receptor (AR), a protein typically associated with prostate cancer, also has a significant role in melanoma, one of the most aggressive skin cancers." (PMID 40940929, 2025). "In the prostate, dysregulated RTK signaling has been implicated in the initiation and progression of prostate cancer, partly through modulation of androgen receptor activity via tyrosine phosphorylation." (PMID 41313502, 2025). "In the prostate, RTK signaling has been implicated in the pathogenesis of prostate cancer, partly through regulation of androgen receptor activity by tyrosine phosphorylation." (PMID 41313502, 2025). "On one hand, the abnormal activation or excessive expression of AR is closely linked to the pathophysiological alterations seen in prostate cancer." (PMID 39963114, 2025). "Cyclin K loss in prostate cancer drives androgen receptor (AR) variant expression and therapy resistance, inducing a BRCA-like deficiency (BRCAness) that increases sensitivity to PARP inhibitors, making it a key target in advanced prostate cancer." (PMID 40075638, 2025). "Our finding is in consistency with prior work showing that non-coding mutations accumulating in prostate cancer are likely perturb the binding affinity of FOXA1 as well as alter the AR cistromes." (PMID 41468516, 2025). "The T877A mutation enhances AR activity in an androgen-deprived environment, promoting the continuous growth of prostate cancer cells." (PMID 40008000, 2025). "Our findings indicated that attenuated LKB1 pathway activity was linked to AR independence in prostate cancer cells." (PMID 39743630, 2025). "AR mutations remain infrequent among treatment naïve prostate cancer patients but are detected in almost 20% of those with castration resistant disease, and in up to 40% of patients who have received ARTA." (PMID 38383885, 2025). "These multifaceted actions underscore their potential to target both ligand-dependent and castration-resistant prostate cancer, including disease driven by AR splice variants." (PMID 41020902, 2025). "Apalutamide, an androgen receptor antagonist for prostate cancer, rarely causes drug‐induced hypersensitivity syndrome (DIHS)." (PMID 40909306, 2025). "In advanced prostate cancer (PC), resistance to AR signaling inhibitors upregulates splice variant ARV7." (PMID 39258426, 2025). "Due to their pivotal roles in tumor progression and therapy resistance, cancer-associated fibroblasts (CAF) are considered key therapeutic targets with loss of stromal androgen receptor (AR) a poorly understood hallmark of aggressive prostate cancer (PCa)." (PMID 41327318, 2025). "Previous research has also uncovered key gene changes linked to the progression of castration-resistant prostate cancer, including mitochondrial adaptations and androgen receptor-independent drivers such as FABP5." (PMID 40491606, 2025).